CTLA4 (cytotoxic T-lymphocyte associated protein 4)
Diseases named in the same sentence as CTLA4 in open-access papers (continued):
Sharing a sentence is not in itself a finding about the gene and the disease.
cancer (continued). "Furthermore, recent years, cancer immunotherapy has shown clear benefits in the survival of cancer patients, especially immune checkpoint inhibitors (ICIs), such as programmed death- 1 (PD-1), programmed death ligand-1 (PD-L1), and cytotoxic T lymphocyte associated antigen 4 (CTLA4) inhibitors." (PMID 34745134, 2021). "Although several immune checkpoints have been discovered, monoclonal antibodies against three major targets (PD1, its ligand PD-L1, and CTLA-4) have been approved for the treatment of a wide variety of cancers." (PMID 33803620, 2021). "The success of anti-PD-1 and CTLA-4 in cancer immunotherapy has stimulated the search for other cancer therapeutic targets." (PMID 34620162, 2021). "Antibodies against immune checkpoints, such as anti-PD-1/PD-L1 and anti-CTLA-4, demonstrate durable clinical benefits in several cancer types." (PMID 33503832, 2021). "The discovery of immune checkpoints, including cytotoxic T lymphocyte-associated protein-4 (CTLA-4) and programmed cell death protein-1 (PD-1, also known as PDCD1), was crucial to the development of cancer immunotherapy and has brought revolutionary changes." (PMID 34298996, 2021). "Cancer immunotherapy consists in the usage of immune checkpoint inhibitors that target CTLA-4, PD-1, and PD-L1, to activate or restore the immune system and counteract the resistance of cancer cells to the immune responses." (PMID 33926465, 2021). "Antibodies targeting the inhibitory T cell receptors CTLA-4 and PD-1 have significantly improved patient survival in many cases, but numerous cancers remain refractory to this approach." (PMID 33564072, 2021). "The blockade of CTLA-4 by monoclonal antibodies such as ipilimumab and tramelimumab promotes T cell killing activity against cancer cells." (PMID 34445720, 2021). "The first antibodies that progressed into clinical trials after showing promising results in cancer treatment were ipilimumab, tremelimumab and quavonlimab, three anti-CTLA-4 antibodies." (PMID 33800368, 2021). "The cytotoxic T lymphocyte antigen 4 (CTLA4) or programmed cell death 1 (PD-1)/PD-1 ligand 1 (PD-L1) axis is approved for use in a variety of cancer types." (PMID 34326876, 2021). "Both clusters also exhibited a cancer-specific exhaustive signature characterized by higher expression of checkpoint molecules (CTLA-4, LAG3, TIGIT)." (PMID 34921160, 2021). "As the first available ICI, the humanized CTLA-4 antibody ipilimumab has revolutionized clinical cancer care and prolonged the 10-year survival for metastatic melanoma." (PMID 34088360, 2021). "Programmed cell death-1 (PD-1), its associated ligand (PD-L1), and cytotoxic T-lymphocyte associated antigen-4 (CTLA-4) negatively regulate immune function and are constitute targets for cancer immunotherapy." (PMID 33446685, 2021). "Antitumor immune responses can be promoted and utilized to treat cancer via immune checkpoint blockade with use of agents such as PD-1/PD-L1 and CTLA-4 inhibitors." (PMID 34970273, 2021). "Immune checkpoint inhibitors (ICIs), such as anti-programmed cell death-1 (PD-1), anti-programmed cell death ligand-1 (PD-L1), and anti-cytotoxic T-lymphocyte antigen-4 (CTLA-4), have revolutionized the treatment of cancer in the past decades." (PMID 34777387, 2021). "CTLA-4 has been well-established as a negative regulator of peripheral T cell tolerance and autoreactivity, and is involved cancer immune evasion." (PMID 34531847, 2021). "FTH1 levels were positively related to PD-1 in 4/32 (12.5%) cancers, PD-L1 in 9/32 (28.1%), CTLA4 in 7/32 (21.9%), TIM-3 in 20/32 (62.5%), LAG3 in 2/32 (6.3%), and LAIR1 in 19/32 (59.4%)." (PMID 33864445, 2021). "Over the past decade, cancer immunotherapy has revolutionized the treatment of cancer with the approval of monoclonal antibodies targeting coinhibitory immune checkpoints, CTLA-4 and PD-1/PD-L1." (PMID 34885161, 2021).
cancer (continued). "The results revealed that PDCD1, IDO1, and CTLA4 were significantly upregulated in cluster 3 patients compared with cluster 1 patients in multiple cancer types." (PMID 33627136, 2021). "Understanding how anti-CTLA-4 and anti-PD-1 checkpoint blockade therapies work will be critical for effectively combining them with other anti-cancer therapeutic approaches such as immune-, radio-, chemo- and targeted therapy to improve overall response rate." (PMID 34774008, 2021). "The results encourage further research on the efficacy of patient-derived DC-CIK cells combined with anti CTLA-4 nanobodiesforthe treatment of malignant tumors." (PMID 34525966, 2021). "Immune checkpoint inhibitors (ICIs; antibodies that block T cell co‐inhibitory receptors such as PD‐1 and CTLA‐4) have revolutionized the treatment of some cancers." (PMID 32920841, 2021). "These drugs block the CTLA-4 activity and determine the activation of T cells with the onset of the immune response and death of cancer cells." (PMID 34638281, 2021). "As a result, CTLA-4 decreases helper T cell activity and increases regulatory T cell activity, which further inhibits the adaptive immune response to cancer." (PMID 34440865, 2021). "Clinical trials on applying mRNA cancer vaccines with anti-PD-1, anti-PD-L1, or anti-PD-L1 plus anti-CTLA-4 mAbs in solid tumors are ongoing." (PMID 33801815, 2021). "PD-L1 was positively correlated with LEPROT in all cancer studies, and PD-1 and CTLA-4 were limited related to LEPROT." (PMID 34804118, 2021). "In order to boost T cell responses against cancer cells, combinations of two checkpoint inhibitors (Durvalumab and Tremelimumab) targeting the CTLA-4 and PD-1/PDL-1 axes have been evaluated." (PMID 34638420, 2021). "The increase popularity of immunotherapy, including anti-PD1/PD-L1, and anti-CTLA-4 therapies, has shown great success in the treatment of human cancer, particularly in solid tumors." (PMID 34354750, 2021). "Drugs that antagonize CTLA-4 and PD-1 can greatly improve the treatment outcomes in late-stage cancer." (PMID 33955820, 2021). "These authors suggested that local IONP-mediated photothermal therapy combined with ICI, such as anti-CTLA-4, can allow immunosuppression mediated by Treg to be overcome, thus boosting cancer immunotherapy." (PMID 33800368, 2021). "Immune checkpoint inhibitors (ICIs), such as antibodies against CTLA-4, PD-1, and its ligand PD-L1, can restore immune cell activation, which aids anticancer immune responses for cancer immunotherapy." (PMID 34948368, 2021). "Recent works have shown the valuable role of combined radiation and anti-CTLA-4 in the local and systemic control of cancer." (PMID 35008319, 2021). "At present, mAbs against CTLA4 are used for treatment of certain cancers in most countries and blockers of PD1 are very close to being approved because of the many clinical trials that have shown promising results." (PMID 33924844, 2021). "Cancer cells can also signal to the immune predators in the tumor through expression of immune checkpoints on the cancer cells, such as PD-L1 and CTLA4, or through secretion of soluble immunosuppressive factors, such as TGF-β, IL-10, and soluble WNTs." (PMID 34703824, 2021). "The 2018 Nobel Prize in Physiology and Medicine was awarded to Tasuku Honjo and James Allison for their discoveries of PD-1 and CTLA-4, respectively, and the impact these discoveries made on clinical cancer care." (PMID 35047501, 2021). "Clinical experience has shown that only 15–25% of patients with various types of cancer respond to anti-CTLA-4 or anti-PD-1/PD-L1, and the treatment prolongs survival by only 3.4 months." (PMID 34200480, 2021). "ICIs, such as anti-CTLA-4 and anti-PD-1 antibodies, exhibited satisfactory therapeutic efficacy in several patients with advanced-stage cancers, especially in patients with melanoma." (PMID 34484197, 2021).
cancer (continued). "We found that FTL levels were positively related to PD-1 in 14/32 cancers (43.8%), PD-L1 in 10/32 (31.3%), CTLA4 in 13/32 (40.6%), TIM-3 in 26/32 (81.3%), LAG3 in 13/32 (40.6%), and LAIR1 in 26/32 (81.3%)." (PMID 33864445, 2021). "In recent years, immune checkpoint inhibitors (ICIs) targeting programmed cell death, regarding protein-1 (PD-1), programmed death-ligand 1 (PD-L1) and cytotoxic T-lymphocyte-associated protein 4 (CTLA4), have become another pillar of cancer treatment." (PMID 34440975, 2021). "Immune checkpoints such as PD-1/PD-L1 and CTLA-4 pathways have introduced a new era in cancer treatment, with a number of drugs currently in Phase I-III trials." (PMID 34680355, 2021). "Further studies should be conducted to investigate more valuable PD-L1 and CTLA-4 regulators to improve the efficacy of immunotherapy and facilitate individualized cancer treatment." (PMID 34088360, 2021). "The CD28-related inhibitory receptors crucial for T cell regulation, namely cytotoxic T-lymphocyte-associated protein 4 (CTLA-4) and programmed cell-death protein-1 (PD-1), are highly expressed in human SCC samples and associated with cancer progression." (PMID 33634137, 2021). "Cytotoxic T-lymphocyte antigen-4 (CTLA-4) is a negative regulator of T cell activation, and inhibition of CTLA-4 induces T cell activation and immune surveillance against cancer cells." (PMID 35096867, 2021). "Specifically, ICIs targeting the PD-1/PD-L1 and CTLA-4/B7 axes have yielded great clinical success in many cancer types." (PMID 34831452, 2021). "A number of immune checkpoint proteins were shown to be dysregulated in cancers and infectious diseases, including PD-1/PD-L1, CTLA-4, lymphocyte activation 3 (LAG-3), TIM-3, VISTA, and Indoleamine-2,3 dioxygenase 1 (IDO1)." (PMID 34917131, 2021). "Studies in cancer patients treated with anti-CTLA-4 therapy revealed better response to treatment in patients with a low ratio of Treg cells compared to Teff cells in the TME." (PMID 34268109, 2021). "Rationale: The low response rate of immunotherapy, such as anti-PD-L1/PD-1 and anti-CTLA4, has limited its application to a wider population of cancer patients." (PMID 33391476, 2021). "Monoclonal antibodies have been developed against PD-1/PD-L1 (e.g., pembrolizumab, nivolumab, tezolizumab, aurumab and durvalumab) and CTLA-4 (e.g., ipilimumab and tremelimumab), and their clinical application has launched a new era of cancer treatment." (PMID 34086601, 2021). "Since the FDA approval of ipilimumab (human IgG1 k anti-CTLA-4 monoclonal antibody) in 2011, eight more ICIs have been approved for cancer therapy." (PMID 34208848, 2021). "The four important immune checkpoints (LAG3, TIM3, CTLA-4, and PD-1/PD-L1) were widely used in cancer immunotherapy." (PMID 33643388, 2021). "The FDA approval of anti-CTLA4 and anti-PD-1 treatments has led to a new era in the treatment of cancer through ‘immune checkpoint blockade’." (PMID 33710817, 2021). "The results suggested that UBE2C expression was positively associated with the immune checkpoint-related genes in 31 cancers, which mainly included CD274, CTLA4, HAVCR2, LAG3, PDCD1, PDCD1LG2, SIGLEC15, and TIGIT." (PMID 34858987, 2021). "KN046 is a dual‐targeting inhibitor of immune checkpoints PD‐L1 and CTLA‐4 that attacks cancer cells simultaneously and powerfully from different directions." (PMID 34473430, 2021). "In theory, it is a promising area to reform anti-CTLA4 antibodies and enhance its efficacy of cancer immunotherapy." (PMID 34178691, 2021). "Immunoinhibitors, such as PD-1, PD-L1, and CTLA-4, have gained widespread attention, as they can serve as immune checkpoint targets in multiple cancers to block immunoinhibitory signals and enable to produce effective antitumor responses." (PMID 34938665, 2021).
cancer (continued). "Surprisingly, replacement of Bifidobacterium pseudolongum by inosine, a metabolite produced by this bacterium, in combination with anti-CTLA4 and CpG (a common immunostimulatory anti-cancer compound) led to similar results in this cancer model." (PMID 34658896, 2021). "Ipilimumab is an immune checkpoint inhibitor that can inhibit CTLA-4 on human T cells to activate the immune system and attack cancer cells to achieve the effect of treating cancer." (PMID 33390784, 2021). "CTLA-4 expression in both datasets was significantly higher in the cancer samples than in the control ones." (PMID 34067631, 2021). "Investigations of the inhibition of Nr2f6 in mice that used an ex vivo CRISPR/Cas9-mediated gene ablation of Nr2f6 in T cells prior to therapeutic ACT in conjunction with an approved PD-L1 or CTLA-4 ICB therapy improved this therapeutic anti-cancer activity." (PMID 34073258, 2021). "There are negative-feedback mechanisms to prevent overstimulation, which can be subverted to suppress the immune system in cancer, such as the upregulation of CTLA-4 expression." (PMID 34178688, 2021). "These important findings opened the way to run several clinical trials exploiting mAbs targeting PD‐1, PD‐L1, and CTLA‐4 in cancer immunotherapy for different kinds of cancers." (PMID 33369247, 2021). "Similar to CTLA-4, binding of programmed death-1 (PD-1) by its ligand (PD-L1), which is overexpressed on the surface of some cancer cells, releases signals that inhibit T cell activation and promote tumor-cell evasion." (PMID 33796453, 2021). "The synergistic impact of a combination of anti-CTLA-4 antibodies and cancer vaccines has also been assessed in numerous preclinical studies." (PMID 34360800, 2021). "Less than 2% of the patients included in the TCGA cohort received immunotherapies such as cytokines, cancer vaccines, anti-CTLA-4 therapy, or other monoclonal antibodies." (PMID 33963274, 2021). "In total, all of these suggest that the combination of 4-1BB and CTLA-4 blockade can be a promising approach in cancer immunotherapy." (PMID 34267616, 2021). "The discovery of immune checkpoint molecules PD-1 and CTLA-4 has undoubtedly transformed the field of cancer immunotherapy." (PMID 34054867, 2021). "Other than anti-CTLA-4, several other interventions such as cancer vaccines, oncolytic viruses, and radiotherapy have been adopted to enhance the efficacy of PD-1 blockade therapy." (PMID 33681388, 2021). "CTLA-4 functions as a negative regulator of T-cell effector function and therefore presented as an attractive target for cancer therapy." (PMID 34268109, 2021). "Inhibitors of PD-1 and CTLA-4 have exhibited outstanding anticancer effects in multiple cancers, including BRCA." (PMID 34413268, 2021). "In total 27 patients received cancer immunotherapy in second or further line (14 patients with anti-CTLA4, 8 patients with antiPD-1/PD-L1, 4 patients with anti-mesothelin and 1 patient with oncolytic virus)." (PMID 34725384, 2021). "Many immunotherapeutic drugs including CTLA-4 and PD-1 inhibitors eliminate cancer cells by increasing IFNγ expression." (PMID 34248641, 2021). "Currently, immune checkpoint inhibitors (ICIs), such as those targeting CTLA-4, PD-1, and the PD-L1 axis, have shown good prospects in various types of malignant tumors." (PMID 34937564, 2021). "This study identifies a novel nanobody-based CTLA4 inhibitor for the treatment of canine cancer patients." (PMID 34675296, 2021). "In immunotherapy of cancer, the use of blocking anti–CTLA-4 and anti–PD-1 antibodies have yielded promising results, and the 2018 Nobel Prize was granted to Jim P. Allison and Tasuku Honjo, who are the pioneers in this field." (PMID 34744733, 2021). "Malignant tumors can evade immune killing by stimulating immune checkpoint target genes (such as PD-1, PD-L1, CTLA-4, TGF-β, and HAVCR2)." (PMID 34249015, 2021).
cancer (continued). "CTLA-4-, PD-1-, and PD-L1-specific immune checkpoint antagonists have completely improved the current status of cancer treatment." (PMID 34745261, 2021). "The results of these previous pre-clinical studies have encouraged the development of anti-CTLA-4 antibodies for use in anti-cancer therapy." (PMID 34201650, 2021). "Immune checkpoint inhibitors (ICI) targeting CTLA-4 and the PD-1/PD-L1 axis have unprecedentedly improved global prognosis in several types of cancers." (PMID 34208848, 2021). "Inhibition of the immune checkpoints using monoclonal antibodies that block the T-cell molecules PD-1, PD-L1, as well as CTLA4 has emerged as a novel anti-cancer treatment with extraordinary survival advantages." (PMID 34277697, 2021). "ICI-based treatments including anti-PD-1/PD-L1, anti-CTLA4, and combinations thereof are increasingly common standards of care for certain forms of cancer." (PMID 34060602, 2021). "At least in mouse models, co-delivery of a probiotic cocktail of Bifidobacterium strains improved the outcome of anti-PDL1 cancer therapy and likewise Bacteroides thetaiotaomicron or Bacteroides fragilis transfer enhanced anti-CTLA-4 cancer therapy." (PMID 33869260, 2021). "Immune checkpoint blockade (ICB), which targets programmed cell death ligand 1 (PDL1) and cytotoxic T lymphocyte antigen 4 (CTLA4) pathways, has become a treatment strategy for various types of cancer." (PMID 34795697, 2021). "LAG-3 is the third inhibitory receptor to be exploited in human anti-cancer immunotherapies, and it is considered a potential next-generation cancer immunotherapy target in human therapy, right next to PD-1 and CTLA-4." (PMID 34067904, 2021). "Among potential biomarkers, CTLA-4 and PD-1 are the leading targets of ICIs in cancer immunotherapy." (PMID 35069558, 2021). "Significantly, over-expression of checkpoint inhibitory molecules, such as CTLA-4, was presented as a strategy of cancer cells to evade the immune system." (PMID 35083014, 2021). "In this regard, clinical achievements in cancer therapy with checkpoint inhibitors (CPI) revealed blocking inhibitory immune checkpoint molecules such as CTLA-4 and human programmed cell death protein 1 (PD1) resulted in significant therapeutic approaches." (PMID 35083014, 2021). "Like other myeloid inhibitory Siglecs (such as Siglec-7 and -9), Siglec-3 has a downstream signaling function similar to other ITIM-containing immune checkpoint receptors like PD-1 and CTLA-4, which are popular checkpoint targets for cancer treatment." (PMID 34827170, 2021). "The combined blockade of the targets CTLA-4 and PD-1 is supposed to synergistically stimulate the immune response against cancer cells." (PMID 33804800, 2021). "Immunotherapy delivered via mAbs targeting immune checkpoint molecules such as CTLA4, PD-1, and PD-L1 has led to a revolution in cancer therapy." (PMID 34035311, 2021). "The main challenge in cancer immunotherapy is now to identify drugs that are able to overcome innate or acquired resistance to anti-PD-1 or anti-CTLA-4 checkpoint-blockade therapies." (PMID 33572260, 2021). "The role of CTLA-4 in cancer immunotherapy was discovered through antibody generation that specifically targets the CTLA-4 glycoprotein." (PMID 33042104, 2020). "Despite successes with checkpoint blockade in many cancers, CTLA‐4 and PD‐1 inhibitors have failed in clinical trials of glioma." (PMID 32392361, 2020). "Programmed death (PD) ligand 1 (PD-L1)/PD1 and cytotoxic T-lymphocyte antigen (CTLA)-4 inhibitors have been used in multiple malignancies, whereas crucial molecules able to disturb other coinhibitory signaling pathways are under investigation." (PMID 33553243, 2020). "The cytotoxic T lymphocyte associated protein 4 (CTLA-4) monoclonal antibody and the programmed death 1 (PD-1)/programed death ligand-1 (PD-L1) pathways are the spotlight of various cancers." (PMID 32998289, 2020).